HYCC2 (hyccin PI4KA lipid kinase complex subunit 2)
Description:
Component of a complex required to localize phosphatidylinositol 4-kinase (PI4K) to the plasma membrane.
Synonyms: FAM126B; MGC39518
Tractability: Antibody: UniProt places it where antibodies can reach, with medium confidence; its Gene Ontology location is reachable by antibodies, with medium confidence. PROTAC: ubiquitination databases record sites on it.
Gene: Protein-coding gene on chromosome 2 (200,973,718 to 201,071,692, reverse strand). Ensembl gene ENSG00000155744.
Subcellular location: Cytoplasm, cytosol; Cell membrane
Subcellular location (Human Protein Atlas): Cell Junctions; Nucleoplasm
Gene Ontology:
Molecular function: protein binding
Biological process: phosphatidylinositol phosphate biosynthetic process; protein localization to plasma membrane
Cellular component: cell junction; plasma membrane; cytosol
Genetic constraint (gnomAD): Loss-of-function variants: 14 observed, 38.15 expected, observed/expected ratio (o/e) 0.37, 90% interval 0.24 to 0.57. The synonymous counts are far from expectation, so gnomAD's model fits this gene poorly and the ratio says little. Missense variants: 367 observed, 499.64 expected, observed/expected ratio (o/e) 0.73, 90% interval 0.67 to 0.8. Synonymous variants: 141 observed, 187.02 expected, observed/expected ratio (o/e) 0.75, 90% interval 0.66 to 0.87.
Homologues: Orthologues: macaque HYCC2 (99% identical), rabbit HYCC2 (96% identical), mouse Hycc2 (95% identical), rat Hycc2 (95% identical), guinea pig HYCC2 (94% identical), dog HYCC2 (93% identical), chimpanzee HYCC2 (90% identical), pig HYCC2 (88% identical), tropical clawed frog hycc2 (76% identical), zebrafish hycc2 (46% identical), zebrafish HYCC2 (29% identical), Drosophila melanogaster Hyccin (24% identical), and 1 more. Paralogues in human: HYCC1 (46% identical).
Diseases named in the same sentence as HYCC2 in open-access papers:
HYCC2 is named in the same sentence as 6 diseases in open-access papers, as found by Europe PMC text mining. Sharing a sentence is not in itself a finding about the gene and the disease.
HYCC2 shares sentences with these, for which no sentence is quoted: cancer (2 papers); colorectal cancer (1); immune complex diseases (1); rheumatoid arthritis (1); skin cancer (1); Tumor (1).